TG (thyroglobulin)
Diseases named in the same sentence as TG in open-access papers (continued):
Sharing a sentence is not in itself a finding about the gene and the disease.
thyroid cancer (continued). "18FDG-PET has been approved for reimbursement for the detection of occult thyroid cancer in patients who have a thyroglobulin greater than 10 ng/mL and have negative radioiodine imaging." (PMID 22530159, 2012). "Fluorodeoxyglucose positron-emission tomography (FDG-PET or PET)/CT imaging is an increasingly more useful tool in the detection of radioiodine-negative, thyroglobulin-positive thyroid cancer." (PMID 22530159, 2012). "The lung metastases from thyroid cancer are positive in thyroglobulin, while this protein is negative either in primary lung cancers or in the tumors originated from other sites." (PMID 21974801, 2011). "These biomarkers, such as CK19, TG, Ki67, Calcitonin, TTF-1, BRAF, RET, HBME-1, and galectin-3, have been translated into clinical practice which offered significant improvement in the preoperative diagnosis of thyroid cancer." (PMID 22188859, 2011). "L-ACs usually exhibit cytoplasmic immunoreactivity of CK7 and negative CK20, while primary thyroid carcinomas show thyroglobulin production." (PMID 21974801, 2011). "Thyroglobulin is a valuable serum marker for detecting recurrent or persistent well-differentiated thyroid cancer of follicular cell origin, as there should be no thyroglobulin present after a total thyroidectomy unless residual thyroid tissue is present." (PMID 24281099, 2010). "Immunocytochemical study with HMB-45 and thyroglobulin antibodies proved to be necessary to confirm a metastatic melanoma and rule out a thyroid carcinoma." (PMID 17263878, 2007). "Moreover, in males, negative complementarity thyroglobulin has been ruled out in primary thyroid carcinoma." (PMID 39851953, 2025). "Thyroglobulin should be measured in any circumstance (at baseline and during follow-up) regardless of whether differentiated thyroid cancer is present." (PMID 38791947, 2024). "From 2004, the WHO classified PDTC as a non-follicular non-papillary, thyroglobulin-producing thyroid carcinoma with an intermediated behaviour between well-differentiated and anaplastic carcinoma, whose distinctive hallmarks of adverse prognosis are high mitotic index and the presence of necrosis." (PMID 34830540, 2021). "Hence, production of thyroglobulin and thyroid hormones appear to be two independent characteristics of differentiated thyroid cancer and probably are not interrelated." (PMID 31049077, 2019). "In contrast, we found that postnatal expression of BRAFV600E under physiologic TSH levels failed to develop thyroid cancers in conditional transgenic Tg(LNL-BrafV600E) mice injected in the thyroid with adenovirus expressing Cre under control of the thyroglobulin promoter (Ad-TgP-Cre)." (PMID 30086162, 2018). "In thyroid cancer patients with biochemically incomplete response to initial treatments, spontaneous decline in thyroglobulin levels without any cancer treatment is a well-known phenomenon; however, spontaneous regression of persistent or recurrent structural disease has not been reported." (PMID 29755799, 2018). "Phospho-PKM2 and Phospho-LDHA could be valuable tumour markers for thyroglobulin negative thyroid cancer." (PMID 25880801, 2015). "The presence of thyroid tumors that appear as cold nodules on thyroid scintigraphy should consider the potential for thyroid carcinoma, if the patient has relatively low serum thyroglobulin concentration in relation to the degree of TSH without thyroglobulin autoantibody." (PMID 22934199, 2012). "First, the patient must undergo total (or near total) thyroidectomy and then receive radioiodine ablation of the remaining thyroid remnant so as to assure that any subsequent thyroglobulin measurements are due to recurrent thyroid cancer and not persistent normal thyroid tissue." (PMID 24281099, 2010).
thyroid cancer (continued). "Cribriform morular thyroid carcinoma can be differentiated from common follicular-cell-derived tumors by the absence of typical mutations; the presence of nuclear and cytoplasmic expressions of β-catenin; the presence of TTF-1, except in morular areas; and the absence of thyroglobulin." (PMID 38835742, 2024). "Importantly, in some patients, serum thyroglobulin was not detectable after the surgery, whereas urinary exosomal thyroglobulin was present, suggesting that it may serve as a potential biomarker of thyroid cancer recurrence." (PMID 36766698, 2023). "In addition to previously discussed cytomorphological pitfalls (see columnar cell variant of PTC), absence of morules, frequent positivity for thyroglobulin, and absence of nuclear beta-catenin expression distinguish these tumors from cribriform-morular thyroid carcinomas." (PMID 32632840, 2020). "Thus, the relationship between serum VAP-1 and thyroid cancer is independent of thyroglobulin." (PMID 27446209, 2016). "However, thyroglobulin and calcitonin indicating thyroid cancer were negative." (PMID 25506006, 2014). "Further, the tumor was negative for thyroglobulin and TTF-1 (excluding thyroid carcinoma), TTF-1 (arguing against a lung primary), and Villin (which helps exclude a carcinoma of digestive tract origin)." (PMID 41584573, 2025). "Immunohistochemically, the tumor is typically positive for PAX8 and negative for PAX2, TTF-1, and thyroglobulin; TTF-1 or thyroglobulin is required to rule out metastases from thyroid cancer." (PMID 29053609, 2017). "Immunohistochemistry result were negative for TTF-1, Thyroglobulin, CD7 and CD20 which ruled out non-small cell lung adenocarcinoma, thyroid cancer and gastrointestinal tract cancer respectively." (PMID 29147330, 2013). "In thyroid cancer, PET MI is useful in patients with metastatic poorly differentiated tumors with high thyroglobulin (Tg) levels and negative 131I whole-body scan results." (PMID 22018056, 2011). "Thyroid carcinoma cells often do not express thyroid-specific genes including sodium iodide symporter (NIS), thyroperoxidase (TPO), thyroglobulin (TG), and thyrotropin-stimulating hormone receptor (TSHR)." (PMID 18682709, 2008). "Anaplastic thyroid cancer cells are characterised by the absence of expression of thyroid-specific genes (TSH receptor, thyroglobulin, and thyroperoxidase)." (PMID 14520435, 2003). "It is a sensitive marker for aggressive types of thyroid carcinomas, such as anaplastic follicular cell-derived thyroid carcinoma, which could be positive even when TTF-1 or thyroglobulin are negative." (PMID 35328664, 2022). "Due to the low expression of thyroglobulin in ATC, it has limited utility as a biomarker in the diagnosis and monitoring of the disease, unlike more differentiated thyroid cancers, where elevated serum thyroglobulin levels may indicate the presence of residual or recurrent disease." (PMID 39744583, 2025).
hyperthyroidism (222 papers, 2003 to 2026). Overactivity of the thyroid gland resulting in overproduction of thyroid hormone and increased metabolic rate. "On univariate regression analysis, age >55 years, duration of goiter ≥5 years, presence of large goiter, compressive neck symptoms, toxic MNG, MNG, hyperthyroidism, total thyroidectomy, and raised serum thyroglobulin (Tg) levels were significantly associated with a DT." (PMID 39996189, 2025). "Although she tested positive for thyroglobulin antibody and transient subclinical hyperthyroidism was observed after two courses, treatment with ICIs was continued." (PMID 38910605, 2024). "Following blood biochemistry, muscle enzyme and thyroid function tests, 1 patient had hyperthyroidism with positive thyroglobulin and anti-thyroid peroxidase antibodies." (PMID 25780436, 2015). "Also overrepresented within cluster 2 are cases positive for anti–thyroid peroxidase (TPO)/thyroglobulin (TG) antibodies and Grave’s hyperthyroidism." (PMID 37379383, 2023). "It is characterized by hyperthyroidism and specific thyroid autoantibodies against thyroid-stimulating hormone receptor (TSHR) and is also commonly accompanied by autoantibodies against thyroglobulin (TG) and thyroid peroxidase (TPO)." (PMID 29259988, 2017). "She presented with subclinical hyperthyroidism (FT4: 1.53 ng/dl, FT3: 3.47 pg/ml, and TSH: 0.011 μIU/ml) and high levels of thyroglobulin (Tg; 742.5 ng/ml)." (PMID 27703446, 2016). "Case 4 had hyperthyroidism due to Hashimoto’s thyroiditis only 1 month after he was diagnosed to have chronic GVHD, his and his donor’s anti-TPO antibody and anti-thyroglobulin antibody were positive." (PMID 26777050, 2015). "We studied the prevalence of overt hypo- and hyperthyroidism and thyroid autoimmunity using medical histories, and measurements of TSH, FT4, anti-TPO and anti-TG, comparing participants exposed to famine at different pregnancy trimesters or born before or conceived after the famine." (PMID 35846325, 2022). "The hormonal assessment revealed hyperthyroidism; TSH was low at 0.142 mUI/L (reference range:0.4-4 mUI/L), T4 was 2 mUI/L (reference range: 0.70-1.4 mUI/L), and the anti-thyroid peroxidase and anti-thyroglobulin antibodies were negative." (PMID 40984930, 2025). "Unlike autoantibodies to thyroglobulin (Tg) or thyroid peroxidase (TPO), thyroid-stimulating TSHR autoantibodies are not just a marker of Graves’ disease but are also held directly responsible for the hyperthyroidism that occurs in most of the patients." (PMID 27895620, 2016). "Further inquiry revealed that her hyperthyroidism had been diagnosed 18 months prior without any relevant symptoms, and approximately 5 months prior, she was diagnosed with GD with high levels of thyroid-stimulating hormone-receptor antibodies (TSH-R-Ab) and thyroglobulin (Tg) at that time." (PMID 38968474, 2024).
autoimmune thyroid disease (203 papers, 2005 to 2025). Inflammatory disease of the thyroid gland due to autoimmune responses leading to lymphocytic infiltration of the gland. "Initial testing revealed positive anti-thyroglobulin antibodies, leading to a suspicion of steroid-responsive encephalopathy associated with autoimmune thyroiditis." (PMID 41446477, 2025). "Hypothyroidism in women of reproductive age is predominantly caused by autoimmune mechanisms, and thyroid peroxidase autoantibodies (TPO-Ab) as well as thyroglobulin autoantibodies (Tg-Ab) are the key markers of underlying thyroid autoimmunity." (PMID 39090762, 2024). "Serum thyroid peroxidase antibody and thyroglobulin antibody are detected in association with the activation of NLRP3 in autoimmune thyroiditis patients." (PMID 36673016, 2023). "Cepharanthine is used to treat autoimmune thyroid disease by blocking T-cell activation through the thyroglobulin peptide Tg2098, a peptide that binds to the arginine-containing HLA-DR variant (DRβ1-Arg74) that causes autoimmune thyroid disease (AITD)." (PMID 37446681, 2023). "An experimental fetal loss model with autoimmune thyroiditis was established after murine thyroglobulin- (mTg-) immunized CBA/J female mice mating with Balb/c males." (PMID 32351559, 2020). "Administration of self-antigen (mouse thyroglobulin; mTg) loaded multi-ligand DCs caused hyporesponsiveness to mTg challenge, suppression of autoantibody production, and amelioration of experimental autoimmune thyroiditis." (PMID 31427630, 2019). "In particular, we observed raised anti thyroperoxidase and thyroglobulin antibodies in the celiac group thus confirming the well-known association between CD and autoimmune thyroiditis." (PMID 29795662, 2018). "On the other hand, TGab tests are recommended in cases of differentiated thyroid cancer together with determination of thyroglobulin, as well as for diagnosing autoimmune thyroid disease in areas deficient in iodine." (PMID 30429677, 2018). "The thyroglobulin gene has been linked to autoimmune thyroid disease and has been suggested to code for Tg forms with different immune reactivity." (PMID 23878745, 2013). "In addition, we detected increased levels of anti-thyroperoxidase and anti-thyroglobulin, autoantibodies commonly associated with autoimmune thyroid diseases, up to five years before the disease diagnosis." (PMID 41107634, 2025). "However, because of the possible negative effects of maternal anti-thyroid antibodies, we underline the importance of monitoring thyroid autoimmunity during pregnancy, including both anti-TG besides anti-TPO antibodies." (PMID 40128881, 2025). "Steroid responsive encephalopathy associated with autoimmune thyroiditis is an autoimmune encephalopathy associated with Hashimoto’s Disease and elevated serum levels of the related antibodies (anti-thyroid-peroxidase antibody or anti-thyroglobulin antibody)." (PMID 26209970, 2015). "The thyroglobulin gene may be a susceptibility gene for autoimmune thyroiditis coding for thyroglobulin variants of different immunogenicity." (PMID 26000316, 2015). "The small number of cases of hypo- and hyperthyroid disease limit our ability to draw conclusions on effects of PBDEs on thyroid disease, but the thyroglobulin results may indicate an increased susceptibility to autoimmune thyroiditis in PBDE-exposed persons." (PMID 19079713, 2008). "It was reported that iodine deficiency might influence thyroid autoimmunity through inflammatory responses induced by oxidative stress, and highly-iodinated thyroglobulin caused by excessive iodine intake was more immunogenic, accelerating the thyroid autoimmune process." (PMID 37469986, 2023). "In another study, associations between vitiligo and anti-TPO (25.6%), anti-thyroglobulin (23.4%), antinuclear (16.8%), and anti-parietal cell (7.8%) antibodies were identified, noting that a total of 74 of the patients had autoimmune comorbidities (41.5%), mainly autoimmune thyroiditis." (PMID 36556267, 2022).
autoimmune thyroid disease (continued). "NOX participation in the production of hydrogen peroxide for the purposes of thyroid hormone synthesis may be associated with the pathophysiology of autoimmune thyroid diseases, through interacting with thyroperoxidase and thyroglobulin (TG) and altering their activity, promoting immunogenicity." (PMID 34573074, 2021). "In patients (mainly women) with autoimmune thyroiditis, metformin was found to decrease thyroid peroxidase and thyroglobulin antibodies." (PMID 40284437, 2025). "A previous meta-analysis demonstrated an elevated breast cancer risk among patients with autoimmune thyroiditis, particularly in those with anti-thyroid peroxidase (anti-TPO) and anti-thyroglobulin (anti-TG) antibodies." (PMID 40567613, 2025). "The detection of thyroglobulin antibodies in patients with HT in subsequent clinical studies has introduced the concept of autoimmune thyroiditis, an immune and inflammatory pathology, in the current literature." (PMID 40428241, 2025). "Autoantibodies to thyroid peroxidase (TPOAb) and thyroglobulin (TgAb) define preclinical autoimmune thyroid disease (AITD), a common endocrine disease characterized by T- and B-lymphocyte infiltration of the thyroid gland." (PMID 38996042, 2025). "Tests for thyroid autoimmunity (anti-peroxidase, anti-TSH receptor, and anti-thyroglobulin antibodies) allow CH to be associated with the trans-placental passage of maternal antibodies." (PMID 40862110, 2025). "In total, 8 out of 29 common pentapeptides were revealed between Mtb immunodominant antigens and human thyroglobulin, which is the major target in autoimmune thyroid disease." (PMID 39765749, 2024). "This patient was diagnosed with autoimmune thyroiditis with elevated anti‐thyroglobulin antibodies but normal thyroid function tests after the ablation." (PMID 38362180, 2024). "Two patients (18.18%) had a clinical history of autoimmune thyroiditis, while another two patients (18.18%) had antithyroid antibodies (anti-thyroglobulin and anti-thyroid peroxidase)." (PMID 38541203, 2024). "The abundance of 18 types of gut bacteria (for example Helicobacter pylori, Yersinia enterocolitica, etc.), was demonstrated to be linked with infection-associated autoimmune thyroiditis and positively correlated with anti-TPO and anti-TG." (PMID 37763034, 2023). "Autoimmune thyroid disease is characterised by the generation of autoantibodies against self-antigens such as thyroid peroxidase, thyroglobulin, and thyroid-stimulating hormone receptor." (PMID 36705201, 2022). "It has been suggested that iodine is more likely to induce thyroid autoimmunity through unmasking a cryptic epitope on thyroglobulin." (PMID 34980104, 2022). "Thyroid dysfunction in pregnant women is mainly caused by the presence of thyroid autoimmunity (TAI), reflected by increased thyroperoxidase (TPO) and/or thyroglobulin (Tg) antibody levels." (PMID 34981747, 2022). "After exposure to an iodine-rich diet, the extent of the autoimmune thyroiditis and the levels of thyroglobulin and TPO autoantibodies were higher in the NOD.H2h4 mice than in the NOD.H2k mice, in which TPO antibodies were essentially absent." (PMID 35572553, 2022). "The adoptive transfer of thyroglobulin-stimulated iNKT cell lines enhanced autoimmune thyroiditis in NOD.H2h4 mice fed with an iodine-rich diet, suggesting that iNKT cells enhanced autoimmune thyroiditis in NOD.H2h4 mice." (PMID 35572553, 2022). "Remarkably, autoimmune thyroiditis and appearance of autoantibodies including anti-thyroperoxidase and anti-thyroglobulin are frequently seen in cancer patients treated with checkpoint inhibitors, particularly with anti-PD1 antibody." (PMID 34021249, 2021). "Thyroid autoimmunity is characterized by easily detectable production of thyroid autoantibodies, to thyroglobulin (TG) and thyroid peroxidase (TPO)." (PMID 34804698, 2021).